ZNF814 (zinc finger protein 814)
Tractability: PROTAC: UniProt records ubiquitination sites on it; ubiquitination databases record sites on it.
Gene: Protein-coding gene on chromosome 19 (57,848,731 to 57,889,074, reverse strand). Ensembl gene ENSG00000204514.
Subcellular location (Human Protein Atlas): Nucleoplasm
Gene Ontology:
Molecular function: transcription cis-regulatory region binding; sequence-specific double-stranded DNA binding
Biological process: negative regulation of transcription by RNA polymerase II; regulation of DNA-templated transcription
Cellular component: nucleus
Genetic constraint (gnomAD): Loss-of-function variants: 8 observed, 8.47 expected, observed/expected ratio (o/e) 0.94, 90% interval 0.55 to 1.65. That is too few expected variants to judge how well the gene tolerates losing a copy. Missense variants: 955 observed, 993.67 expected, observed/expected ratio (o/e) 0.96, 90% interval 0.91 to 1.01. Synonymous variants: 311 observed, 325.88 expected, observed/expected ratio (o/e) 0.95, 90% interval 0.87 to 1.05.
Homologues: Paralogues in human: ZNF33B (29% identical), ZNF229 (28% identical), ZNF658 (28% identical), ZNF226 (28% identical), ZNF235 (28% identical), ZNF112 (28% identical), ZNF33A (28% identical), ZNF30 (27% identical), ZNF484 (27% identical), ZNF841 (27% identical), ZFP28 (27% identical), ZNF227 (27% identical), and 164 more.
Diseases named in the same sentence as ZNF814 in open-access papers:
ZNF814 is named in the same sentence as 6 diseases in open-access papers, as found by Europe PMC text mining. Sharing a sentence is not in itself a finding about the gene and the disease. The quoted sentences say what the papers report.
dengue (1 paper, 2025). "Further characterization of ZNF814, including its interaction with dengue viral components or host signaling pathways (e.g., IFN response), is critical to elucidate its contribution to disease progression." (PMID 41583452, 2025).
uterine tumor (1 paper, 2019).
tumor (1 paper, 2015). "While 15 genes were found to be altered in two or more tumors, only 5 mutations occurred in more than one tumor model (ADCY2 p.V147L, ERBB2 p.I655V, NCF2 p.H308Q, SYNE1 p.L885V, and ZNF814 p.158V)." (PMID 26270481, 2015).
ZNF814 also shares sentences with these, for which no sentence is quoted: bladder cancer (1 paper); cancer (1); neurodegenerative disease (1).